PPFIA1 (PPFI scaffold protein A1)
Diseases named in the same sentence as PPFIA1 in open-access papers (continued):
Sharing a sentence is not in itself a finding about the gene and the disease.
cancer (19 papers, 2010 to 2024). A tumor composed of atypical neoplastic, often pleomorphic cells that invade other tissues. "Phosphorylation ratios were calculated to determine the differences between two samples (PPFIA1-siRNA/NC and miR-181a mimic/NC) at 248 site-specific phosphorylation sites implicated in cancer signaling." (PMID 30825668, 2019). "Considering the location of PPFIA1 in this amplicon, we examined whether protein encoded by PPFIA1, liprin-α1, possesses oncogenic properties in relevant carcinoma cell lines." (PMID 27075696, 2016). "For example, male-amplified genes such as DLG3, PORCN, and PPFIA1 are involved in regulating postsynaptic membrane neurotransmitter receptor levels across multiple cancer types." (PMID 39716176, 2024). "PPFIA1 was primarily localized to the cytoplasm and nucleus of cancer cells, and the expression rate was significantly higher in cancer tissues than in normal tissues (68.0% vs. 25.0%, P < 0.05)." (PMID 37158817, 2023). "Our study found that down-regulation of PPFIA1 expression can significantly reduce the migration and invasion behavior of cancer cells." (PMID 37158817, 2023). "We further assessed PPFIA1 protein expression using an IHC staining-based TMA dataset containing samples from 147 surgically removed cancer tissues and 40 normal esophageal tissues." (PMID 37158817, 2023). "The impact of PPFIA1 on the migration and invasion of cancer cells were investigated by wound-healing and transwell assays, respectively." (PMID 37158817, 2023). "Materials and methods: In this study, several databases, including Oncomine, UALCAN, and the cancer cell line encyclopedia, were used to compare differences in PPFIA1, PPFIA2, PPFIA3, and PPFIA4 expression between normal colon samples and CRCs." (PMID 36605492, 2023). "Two other genes in the amplicon, FADD, and PPFIA1, displayed higher overall correlation across cancer types, implicating these genes as potential novel cancer drivers for further investigation." (PMID 24874471, 2014). "PPFIA1 is frequently amplified and plays a crucial role in cell migration and invasion by affecting cell motility, mediating extracellular matrix degradation and facilitating the formation of lamellipodial protrusions of cancer cells." (PMID 37158817, 2023). "Copy number amplifications are frequently observed in the chromosomal region 11q13, which harbors besides ANO1, genes CCND1, ORAOV1, PPFIA1, FADD and CTTN, the expression of which is associated with cancer proliferation, migration, apoptosis or poorer prognosis." (PMID 33803266, 2021). "PPFIA1 is located at the 11q13 region commonly amplified in cancer." (PMID 30005669, 2018). "We also demonstrated that knockdown of EGFR, BRD9 and PPFIA1, which showed frequently copy-number gain at the genomic level, significantly inhibited cancer cell proliferation, indicating that these genes may play important oncogenic roles in ESCC." (PMID 28548104, 2017). "Our aim herein was to study the function of liprin-α1 and evaluate whether PPFIA1/liprin-α1 possesses oncogenic properties in cancers where it is often amplified." (PMID 27075696, 2016). "Thus, although PPFIA1 is so far the only gene in the liprin family which is commonly amplified in several tumor types, genetic alterations in other liprin family genes, although infrequent, have recently been found to contribute to cancer progression." (PMID 34654889, 2021). "The probable target genes that are amplified and/or overexpressed in different cancers have been reported to include CCND1, FGF4, PPFIA1, CTTN and ORAOV1." (PMID 22920630, 2012). "Despite the location of PPFIA1 in one of the most commonly amplified regions in many epithelial cancers, the role of liprin-α1 in cancer progression has not been studied precisely." (PMID 27075696, 2016).
tumor (11 papers, 2012 to 2025). "High expression levels of PPFIA1 are associated with several adverse clinicopathological features, including deeper tumor invasion, lymph node metastasis, and advanced TNM stage." (PMID 41286778, 2025). "Correlation analysis found that PPFIA1 expression was inversely associated with tumor location (P = 0.011), tumor invasion depth (P = 0.041), lymph node metastasis (P = 0.020), and TNM stage (P = 0.007) in ESCC patients." (PMID 37158817, 2023). "High PPFIA1 mRNA expression was associated with high tumour grade and the development of distant metastasis to the liver, brain, bone and lung (P < 0.05)." (PMID 32410585, 2020). "Likewise, results using the METABRIC cohort revealed that patients with tumours that highly expressed PPFIA1 mRNA significantly associated with poor recurrence and distant metastasis than those with low PPFIA1 expression (P < 0.05)." (PMID 32410585, 2020). "The expression of PPFIA1 mRNA was markedly higher in ESCA tumor samples than in adjacent normal samples according to the GEPIA website." (PMID 37158817, 2023). "In our current study, we observed an increase of PPFIA1 expression in ESCC, which was associated with tumor metastasis and a poorer prognosis." (PMID 37158817, 2023). "High PPFIA1 expression was closely related to several clinicopathological characteristics, including tumor location, histological grade, tumor invasion depth, lymph node metastasis, and tumor-node-metastasis (TNM) stage." (PMID 37158817, 2023). "Overall PPFIA1 expression in various tumor specimens, as well as in normal controls, were further analyzed with the Oncomine database." (PMID 37158817, 2023). "PPFIA1 mRNA expression was obviously increased in the tumor tissues versus normal tissues from most of the datasets for all types of tumors." (PMID 37158817, 2023). "Taken together, these findings suggest a key role of PPFIA1 in the invasion of luminal tumours and response to treatment." (PMID 32410585, 2020). "We have demonstrated that PPFIA1 mRNA was positively correlated with CCND1 mRNA levels in cases with luminal tumours." (PMID 32410585, 2020). "PPFIA1 is part of a multi-protein complex that is important in the regulation of tumour cell migration and invasion." (PMID 32410585, 2020). "In this study, we show that patients with luminal tumours and higher expression of PPFIA1 are less likely to benefit from endocrine therapy." (PMID 32410585, 2020). "Protein expression of PPFIA1 was observed in the cytoplasm of luminal tumours, and a representative images of IHC staining are shown in." (PMID 32410585, 2020). "High PPFIA1 protein expression (> 15 H-score) was observed in 394/521 (76%) of cases in luminal tumours, while high expression of PPFIA1 mRNA was observed in 1129/1398 (81%) of cases in the METABRIC cohort." (PMID 32410585, 2020). "The average body weight of mice receiving NC-siRNA treatment at the time of tumor inoculation was 27.9 g, and this reduced to 26.4 g on day 21, whereas it increased from 27.9 to 28.4 g in mice receiving PPFIA1-siRNA treatment (p = 0.02)." (PMID 30825668, 2019). "It is worth mentioning that the expression of PPFIA1 was only correlated with the degree of tumor differentiation in the cDNA chip dataset, which might be due to the limited sample size in the research." (PMID 37158817, 2023). "However, our finding confirmed an oncogenic role of PPFIA1 in tumour cell invasion where we found high PPFIA1 levels is significantly correlated with the development of distant metastasis in the liver." (PMID 32410585, 2020). "This study has explored the potential effects of PPFIA1 expression in luminal tumours." (PMID 32410585, 2020).
tumor (continued). "Also, PPFIA1 acts as a tumor suppressor and regulates cell motility by interacting with ING4." (PMID 24886289, 2014). "Because the hazard score was associated with perineural invasion status of invasive ductal cancer of the breast, we may speculate that combination of TMEM16A, FADD and PPFIA1 expressions influence the invasiveness of the tumor cells and affect the ultimate prognosis of these cases." (PMID 24886289, 2014). "To determine the clinical value of PPFIA1 in ESCC, we analyzed the difference in the expression of this novel marker in tumor tissues compared with normal tissues and assessed its correlation with the survival of ESCC patients using multiple datasets." (PMID 37158817, 2023). "A previous study showed that silencing of PPFIBPI causes a significant decrease of cell migration and it was demonstrated that PPFIA1 and PPFIBPI may co-operate in the regulation of tumour cell migration." (PMID 32410585, 2020). "Although the role of PPFIA1 in tumor cell progression has been well verified, it is not clear whether its dysregulation is related to metastasis risk or prognosis in ESCC patients." (PMID 37158817, 2023).
PPFIA1 also shares sentences with these, for which no sentence is quoted: ovarian carcinoma (2 papers); acute lung injury (1); Arrhythmia (1); esophageal squamous cell carcinoma (1); glioblastoma (1); glioma (1); ischemic stroke (1); laryngeal carcinoma (1); lung adenocarcinoma (1); lung carcinoma (1); neurological disorders (1); non-small cell lung carcinoma (1); oropharyngeal carcinoma (1); pancreatic adenocarcinoma (1); squamous cell carcinoma (1); thymoma (1).